STK38 (serine/threonine kinase 38)
Description:
Serine/threonine-protein kinase that acts as a negative regulator of MAP3K1/2 signaling. Converts MAP3K2 from its phosphorylated form to its non-phosphorylated form and inhibits autophosphorylation of MAP3K2. Acts as an ufmylation 'reader' in a kinase-independent manner: specifically recognizes and binds mono-ufmylated histone H4 in response to DNA damage, promoting the recruitment of SUV39H1 to the double-strand breaks, resulting in ATM activation.
Synonyms: NDR1; NDR
Tractability: Small molecule: a structure with a bound ligand is known; a high-quality ligand is known; it belongs to a druggable protein family. PROTAC: it is named in the literature on targeted protein degradation; UniProt records ubiquitination sites on it; ubiquitination databases record sites on it; its protein half-life has been measured; a small molecule that binds it is known.
Target class: Kinase; Enzyme; Protein Kinase; AGC protein kinase group; AGC protein kinase NDR family
Gene: Protein-coding gene on chromosome 6 (36,493,880 to 36,547,516, reverse strand). Ensembl gene ENSG00000112079.
Subcellular location: Nucleus; Cytoplasm; Chromosome
Subcellular location (Human Protein Atlas): Cytosol
Pathways (Reactome):
Signal Transduction: RHOBTB1 GTPase cycle; RHOBTB2 GTPase cycle
Gene Ontology:
Molecular function: ATP binding; cadherin binding; histone reader activity; magnesium ion binding; mitogen-activated protein kinase kinase kinase binding; protein binding; protein serine kinase activity; protein serine/threonine kinase activity; ubiquitin-like protein reader activity; UFM1-modified protein reader activity; protein kinase activity
Biological process: DNA damage checkpoint signaling; DNA damage response; intracellular signal transduction; negative regulation of MAP kinase activity; protein modification process; protein phosphorylation; chromatin organization; postsynapse organization
Cellular component: chromosome; cytoplasm; cytosol; nucleus; site of double-strand break; glutamatergic synapse
Genetic constraint (gnomAD): Loss-of-function variants: 24 observed, 52.82 expected, observed/expected ratio (o/e) 0.45, 90% interval 0.33 to 0.64. The upper end of that interval is the gene's LOEUF score, 0.64, which puts it in group 2 of 6, group 1 being the genes least tolerant of losing a copy. Missense variants: 428 observed, 584.93 expected, observed/expected ratio (o/e) 0.73, 90% interval 0.68 to 0.79. Synonymous variants: 175 observed, 185.8 expected, observed/expected ratio (o/e) 0.94, 90% interval 0.83 to 1.07.
Homologues: Orthologues: chimpanzee STK38 (100% identical), macaque STK38 (100% identical), guinea pig STK38 (99% identical), pig STK38 (99% identical), mouse Stk38 (99% identical), rat Stk38 (99% identical), tropical clawed frog stk38 (93% identical), zebrafish stk38a (92% identical), rabbit STK38 (92% identical), zebrafish stk38b (89% identical), Drosophila melanogaster trc (69% identical), Caenorhabditis elegans sax-1 (65% identical). Paralogues in human: STK38L (87% identical).
Diseases named in the same sentence as STK38 in open-access papers:
STK38 is named in the same sentence as 53 diseases in open-access papers, as found by Europe PMC text mining. Sharing a sentence is not in itself a finding about the gene and the disease. The quoted sentences say what the papers report.
lung carcinoma (4 papers, 2016 to 2023). "In lung adenocarcinoma, DIAPH3 binds to STK38 protein and activates extracellular signal-regulated kinase signal transduction, promoting the growth of lung cancer cells." (PMID 36750200, 2023). "A highly expressed level of STK38 was related to a poor PPS and DMFS for breast cancer and poor OS and FP for lung cancer, however, a lowly expressed STK38 was linked to a poor OS and RFS for breast cancer and a poor PPS for lung cancer." (PMID 36232893, 2022). "DIAPH3 has been identified as the binding protein of STK38 that impairs the interaction between STK38 and MEKK and activates ERK signaling to trigger off tumorigenesis of lung cancer." (PMID 34405015, 2021).
gastric cancer (3 papers, 2021 to 2022). A primary or metastatic malignant neoplasm involving the stomach. "According to researchers, Kir2.1 can be coupled with Stk38 to regulate the process of epithelial‐mesenchymal transition (EMT) and promote the invasion and metastasis of human gastric cancer cells." (PMID 34592781, 2021). "However, a high STK38 expression was correlated with a poor clinical outcome, particularly in patients with LGG, gastric cancer and liver cancer, based on the Kaplan–Meier analysis." (PMID 36232893, 2022). "A high expression of STK38 was correlated with the poor OS, PPS, FP and PFS in gastric cancer." (PMID 36232893, 2022).
cardiomyopathies (2 papers, 2017 to 2020). "This furthers our understanding of the regulatory mechanism of cardiac sarcomere assembly in both physiologic and pathologic contexts, and uncovers a potential novel pathway to cardiomyopathy through modulating the Stk38/Rbm24 protein activity." (PMID 28322254, 2017).
esophageal cancer (2 papers, 2020 to 2022). A primary or metastatic malignant neoplasm involving the esophagus. "The statistically higher expressions of PLAUR, BIK, DRAM2, RNF41, STK38, ATG5, and PARP1 were measured in esophageal cancer than those in normal tissue, while statistically significant differences were also detected between ESCC and esophageal adenocarcinoma (EAC)." (PMID 32974198, 2020).
lung adenocarcinoma (2 papers, 2022 to 2023). A carcinoma that arises from the lung and is characterized by the presence of malignant glandular epithelial cells. "Some studies have demonstrated the oncogenic potential of the STK38 gene in progressive ductal carcinoma in situ in the breast tissue, lung adenocarcinoma and ovarian cancer." (PMID 36232893, 2022).
prostate carcinoma (2 papers, 2022 to 2026). A carcinoma that arises from epithelial cells of the prostate gland. "Given that STK38 has previously been reported to inhibit β-catenin activity in prostate cancer, we hypothesized that STK38 might modulate GSK3β substrate preference in pRCC." (PMID 41540036, 2026). "Past studies have reported that the STK38 expression was higher in primary prostate cancer than it was in metastasis cancer, and that it could be a potential tissue biomarker during tumor progression." (PMID 36232893, 2022). "STK38 was also discovered to inhibit the metastasis of prostate cancer both in vitro and in vivo." (PMID 36232893, 2022).
acute lung injury (1 paper, 2017). A condition of lung damage that is characterized by bilateral pulmonary infiltrates (pulmonary edema) rich in neutrophils, and in the absence of clinical heart failure. "STK38 encodes for serine-threonine kinase 38, an inhibitor of mitogen-activated protein (MAP) kinase 1 signaling has been linked to protection from nickel-induced acute lung injury." (PMID 28521775, 2017).
colon adenocarcinoma (1 paper, 2022). "On the contrary, a low expression of STK38 was discovered in four cancers: breast invasive carcinoma (BRCA), kidney chromophobe (KICH), colon adenocarcinoma (COAD) and prostate adenocarcinoma (PRAD)." (PMID 36232893, 2022).
diabetes (1 paper, 2023). "Given the fact that the worldwide prevalence of rate of NAFLD is strongly linked to diabetes and insulin resistance, we were keen to assess the effect of STK38 on lipid homeostasis." (PMID 37028764, 2023).
epilepsy (1 paper, 2025). A brain disorder characterized by episodes of abnormally increased neuronal discharge resulting in transient episodes of sensory or motor neurological dysfunction, or psychic dysfunction. "Sgk3, Gsk3a, and Stk38, as well as other stress kinases that we found to be overexpressed in the brainstem, such as Map3k13, have been less well-studied in the context of epilepsy." (PMID 41511350, 2025).
glioblastoma multiforme (1 paper, 2022). "On the contrary, STK38 could reduce the proliferation and colony formation of glioblastomas." (PMID 36232893, 2022).
head and neck squamous cell carcinoma (1 paper, 2022). A squamous cell carcinoma that arises from any of the following anatomic sites: lip and oral cavity, nasal cavity, paranasal sinuses, pharynx, larynx, and salivary glands. "We found that there is a positive correlation between the infiltration level of the tumor-associated fibroblasts and expression of STK38 for head and neck squamous cell carcinoma-HPV-(HNSC-HPV-), LGG, PAAD, PRAD, SARC, TGCT and UCS as based on all or most of the algorithms." (PMID 36232893, 2022).
Hepatic steatosis (1 paper, 2023). Steatosis is a term used to denote lipid accumulation within hepatocytes. "Reduced STK38 (HFD+shRNA STK38) ameliorates HFD-induced impaired glucose tolerance, insulin resistance, and hepatic steatosis in HFD mice mainly by controlling hypophosphorylation of TBK1." (PMID 37028764, 2023).
hypertriglyceridemia (1 paper, 2023). A laboratory test result indicating elevated triglyceride concentration in the blood. "Notably, ectopic expression of STK38 in mouse liver leads to lean NAFLD phenotype with hepatic inflammation, insulin resistance, intrahepatic lipid accumulation, and hypertriglyceridemia in mice fed on a regular chow diet." (PMID 37028764, 2023).
Insulin resistance (1 paper, 2023). Increased resistance towards insulin, that is, diminished effectiveness of insulin in reducing blood glucose levels. "To find the association between STK38-mediated occurrence of insulin resistance with inflammation, we investigated NF-κβ′s subcellular localization." (PMID 37028764, 2023). "Further, we investigated if TBK1 pharmacological inhibition using Amlexanox can rescue the insulin resistance in STK38-overexpressing HepG2 Cells." (PMID 37028764, 2023). "Our study broadens the role of STK38 with pathophysiological implications for hepatic insulin resistance and lipid accumulation." (PMID 37028764, 2023). "Taking it all together, our data strongly suggest that STK38 knockdown can ameliorate diet-induced impaired glucose tolerance and hepatic insulin resistance." (PMID 37028764, 2023). "Here, we show that HFD induces the expression of hepatic serine/threonine kinase 38 (STK38), which further induces systemic inflammation leading to insulin resistance." (PMID 37028764, 2023). "Moreover, hepatic STK38 depletion mice are protected against HFD-induced insulin resistance, hepatic inflammation, and NAFLD." (PMID 37028764, 2023). "For one stimulus, STK38 binds to Tank-Binding protein Kinase 1 and induces Tank-Binding protein Kinase 1 phosphorylation to promote NF-κβ nuclear translocation that mobilizes the release of proinflammatory cytokines and eventually leads to insulin resistance." (PMID 37028764, 2023). "Taken together, these results suggest that an elevated expression of hepatic STK38 may exacerbate hepatic and systemic insulin resistance." (PMID 37028764, 2023). "Thus, our study highlights that STK38 can be a potential target to explore the missing link between those diet-induced molecular alterations that can induce hepatic inflammation and insulin resistance that can develop the lean fat phenotype." (PMID 37028764, 2023). "Next, we analyzed if STK38 knockdown in HFD can improve HFD-induced hepatic insulin resistance." (PMID 37028764, 2023). "Overexpression of STK38 in regular diet mice develop lean NAFLD-related metabolic disorders and showed increased inflammation and insulin resistance with enhanced intrahepatic lipid accumulation." (PMID 37028764, 2023). "Our study suggests that STK38 is a critical node of the lipogenic/immune axis and provides a potential therapeutic target to ameliorate inflammation and insulin resistance in lean and nonlean NAFLD." (PMID 37028764, 2023). "Based on the observations, we propose STK38 increase the expression of some inflammatory cytokines via TBK1 signaling pathways, both of which are involved in the pathogenesis of hepatic as well systemic insulin resistance by interfering with insulin signaling and action." (PMID 37028764, 2023). "Thus, our study suggests that STK38 is a critical node of the lipogenic/immune axis and provides a potential therapeutic target to ameliorate inflammation and insulin resistance in lean and nonlean NAFLD." (PMID 37028764, 2023).
lentivirus infection (1 paper, 2017). Virus diseases caused by the Lentivirus genus. "A reduction in Stk38 as well as Rbm24 was observed 2 days after shStk38 lentivirus infection." (PMID 28322254, 2017).
lipodystrophy (1 paper, 2023). A congenital or acquired disorder characterized by abnormal loss or redistribution of the adipose tissue in the body. "Furthermore, we explored if STK38 knockdown can attenuate HFD-mediated lipodystrophy." (PMID 37028764, 2023).
liver cancer (1 paper, 2022). An epithelial or non-epithelial malignant neoplasm that arises from the liver. "Moreover, a high level of STK38 expression was related to a poor OS, RFS and PFS for liver cancer." (PMID 36232893, 2022).
metabolic syndrome (1 paper, 2024). A cluster of metabolic risk factors for CARDIOVASCULAR DISEASES and TYPE 2 DIABETES MELLITUS. "A liver-specific KO of Stk38 ameliorated high-fat-died (HFD) induced insulin resistance, hepatic inflammation, and lipid accumulation, as well as can reduce the cholesterol and triacylglycerol (TAG) levels, which are major indicators of metabolic syndrome." (PMID 38803357, 2024).
metastatic tumor (1 paper, 2022). "Notably, the STK38 expression in skin cutaneous melanoma (SKCM) primary tissue was lower than it was in the respective metastatic tumor tissue." (PMID 36232893, 2022).
neuroblastoma (1 paper, 2025). Neuroblastoma (NB) is the most common solid, extracranial childhood tumor. "One study has shown that the STK38 modulation of MYCN protein activity and abundance results in the loss of viability of MYCN-amplified neuroblastoma cells." (PMID 41142119, 2025).
ovarian carcinoma (1 paper, 2022). A malignant neoplasm originating from the surface ovarian epithelium. "On the contrary, a low STK38 expression was associated with a poor OS and PFS prognosis for ovarian cancer." (PMID 36232893, 2022). "A lower STK38 expression in the tumors was discovered in ovarian cancer, COAD and LUAD." (PMID 36232893, 2022). "The result from the CPTAC analysis showed that a higher STK38 protein expression in cancer was discovered in PAAD, ccRCC and LIHC, and the expression of STK38 total proteins was lower in ovarian cancer, COAD and LUAD when they were compared to the normal tissues." (PMID 36232893, 2022).
pancreatic cancer (1 paper, 2023). "The interaction between Caprin-1 and STK38 in pancreatic cancer cells were then confirmed." (PMID 38082307, 2023).
papillary renal cell carcinoma (1 paper, 2026). A rare subtype of renal cell carcinoma, arising from the renal tubular epithelium and showing a papillary growth pattern, which typically manifests with hematuria, flank pain, palpable abdominal mass or nonspecific symptoms, such as fatigue, weight loss or fever. "Collectively, our findings identify STK38 as a novel mediator of signaling heterogeneity and a promising therapeutic target in papillary renal cell carcinoma." (PMID 41540036, 2026).
rectum adenocarcinoma (1 paper, 2022). An adenocarcinoma arising from the rectum. "A low expression of STK38 was related to a poorer overall survival (OS), including in kidney renal clear cell carcinoma (KIRC), rectum adenocarcinoma (READ) and thymoma (THYM)." (PMID 36232893, 2022).
uterine cancer (1 paper, 2022). Primary or metastatic malignant neoplasm involving the uterine corpus and/or the cervix. "The highest mutation frequency of STK38 happened in the uterine cancer patients, and the “mutation” accounted for the majority of all the alterations." (PMID 36232893, 2022).
cancer (16 papers, 2012 to 2026). A tumor composed of atypical neoplastic, often pleomorphic cells that invade other tissues. "In general, STK38 shows a significant prognostic value in different cancers and is closely associated with cancer immunity." (PMID 36232893, 2022). "We used a variety of algorithms to analyze the potential relationship between the infiltration level of cancer-associated fibroblasts and STK38 gene expression in different cancer types of TCGA." (PMID 36232893, 2022). "We firstly analyzed the genetic mutation status of STK38 in the cancer patients in the TCGA database." (PMID 36232893, 2022). "The expression of STK38 was up-regulated in several cancers and associated with cancer immunity." (PMID 37046714, 2023). "Recently, a pan-cancer analysis of STK38 reveals that the expression of STK38 is associated with patient survival, immune cell infiltration such as NK cells, cancer-associated fibroblasts, tumor mutation burden and microsatellite instability in several human cancers." (PMID 37046714, 2023). "Interestingly, somatic mutations in STK38 are known in normal and tumor tissues of cancer patients." (PMID 37046714, 2023). "If an association between HEY1 phosphorylation status and the cancer phenotype can be found, STK38, STK38L and other serine/threonine kinases responsible for the phosphorylation of HEY1 at Ser-68 may represent novel attractive targets for therapeutic intervention." (PMID 27129302, 2016). "Previous studies have reported context-dependent roles of STK38 across different cancers, with both tumor-promoting and suppressive functions described depending on signaling context." (PMID 41540036, 2026). "This polypeptide promotes cancer growth by inhibiting the binding between serine/threonine kinase 38 (STK38) and SMAD-specific E3 ubiquitin protein ligase 1 (SMURF1), which prevents MEKK2 from undergoing ubiquitination and proteasomal degradation." (PMID 38835343, 2024). "STK38 is involved in malignant tumor invasion and metastasis, cancer stem cells, and even development." (PMID 37046714, 2023). "The STK38 mRNA expression levels have been reported as up-regulated in breast, ovarian, and lung cancers." (PMID 37046714, 2023). "STK38 is involved in malignant tumor invasion and metastasis, and its overexpression leads to chromosomal instability." (PMID 37046714, 2023). "In our study, we found that STK38 expression is associated with the TMB in eight kinds of cancers and with STK38 expression being associated with the MSI in five kinds of cancer." (PMID 36232893, 2022). "Meanwhile, a prognosis analysis showed that a distinct relationship existed between STK38 expression and the clinical prognosis of cancer patients." (PMID 36232893, 2022). "We screened out the top three cancers with the strongest correlation between the STK38 expression and the ImmuneScore or StromalScore based on the TCGA cohort." (PMID 36232893, 2022). "We firstly analyzed the expression of STK38 in various of cancers using the TCGA and CPTAC datasets." (PMID 36232893, 2022). "First, although the pan-cancer analysis has provided us with some important insights on STK38 in tumors, it is essential to conduct related experiments to verify our results." (PMID 36232893, 2022). "Next, we will perform biological experiments to explore the mechanism of STK38 in different cancers." (PMID 36232893, 2022). "Cancer patients were divided into high- and low-expression groups, and then we analyzed the correlation between the STK38 expression levels and the clinical outcome of patients with different cancers." (PMID 36232893, 2022). "To deeply explore the molecular biological mechanism of STK38 in cancer initiation and progression, we obtained the STK38-interacting proteins and the STK38 expression correlated genes to perform pathway enrichment analyses." (PMID 36232893, 2022). "The results demonstrated the strong relationship between STK38 expression and immune infiltration level in several cancers." (PMID 36232893, 2022).